PAX6 (paired box 6)
Diseases named in the same sentence as PAX6 in open-access papers (continued):
Sharing a sentence is not in itself a finding about the gene and the disease.
aniridia (continued). "The authors analyzed phenotypic data of 43 individuals diagnosed with aniridia or aniridia-like phenotypes and grouped them according to the type of mutation found in the PAX6 gene (loss-of-function mutations, missense mutations, and COOH-terminal extension (CTE) mutations)." (PMID 22509105, 2012). "A mutation in the PAX6 gene was confirmed to be capable of causing the classic aniridia phenotype." (PMID 22815628, 2012). "Most of PAX6 mutations are found in exons 5–14, causing various severe phenotypes in the eye such as aniridia, cataract and possibly myopia, all of which could eventually lead to blindness." (PMID 22550392, 2012). "Numerous PAX6 mutations have been detected in patients with aniridia." (PMID 22509105, 2012). "The majority of mutations in congenital aniridia have been found in the paired box 6 gene (PAX6)." (PMID 22550392, 2012). "In addition, cases of ARS have been described associated with a deletion of PAX6, and cases of bilateral aniridia with proven PITX2 and FOXC1 mutations." (PMID 21617748, 2011). "In this study, the aniridia in both families was caused by large deletions in the PAX6 region." (PMID 21364908, 2011). "Thus even in the setting of enhanced homozygosity from recent shared parental ancestry, heterozgyous PAX6 mutation typically underlies the phenotype of classic aniridia." (PMID 21423868, 2011). "Mutations in PAX6 (OMIM 607108) have been shown to be responsible for aniridia in most patients." (PMID 21850189, 2011). "Mutations in PAX6 were identified in three unrelated probands with aniridia and cataract." (PMID 20806047, 2010). "Most previous mutations of PAX6 have been associated with aniridia." (PMID 20405024, 2010). "Mutations or deletions of PAX6 were first identified in patients with aniridia." (PMID 20806047, 2010). "Furthermore, mutation of the corresponding threonine (T63P) in the human PAX6 gene results in a relatively mild form of aniridia characterized by subtle iris hypoplasia, cataract and keratopathy along with nystagmus." (PMID 20221250, 2010). "Recently, our group has carried out resequencing analysis of the gene in autistic patients with aniridia, with the aim of searching for additional mutations of PAX6, which might be associated with the disease." (PMID 21203536, 2010). "In addition, WAGR syndrome (Wilms tumor, Aniridia, Genitourinary anomalies, and mental Retardation) is associated with a contiguous gene deletion which includes PAX6 and the WT1 gene (WT1)." (PMID 20806047, 2010). "In this study we identified five PAX6 mutations in 17 patients with congenital eye anomalies, resulting in a mutation detection rate of approximately 30% (5/17) in all patients with congenital eye anomalies or 83% (5/6) in patients with aniridia." (PMID 19898691, 2009). "Mutations in the paired box 6 (PAX6)gene cause a wide variety of eye anomalies, including aniridia." (PMID 19898691, 2009). "We identified two novel PAX6 mutations in families with severe aniridia." (PMID 19862335, 2009). "We identified eight different causal PAX6 mutations in nine unrelated cases with isolated aniridia." (PMID 18776953, 2008). "We performed a mutation analysis for PAX6 in 70 unrelated patients with isolated aniridia." (PMID 18483559, 2008). "We performed a mutation analysis for PAX6 in 70 unrelated patients with aniridia." (PMID 18483559, 2008). "Our results indicate that the mechanism by which null PAX6 mutations cause aniridia might be either haploinsufficiency of the full-length PAX6 protein or an aberrant ratio of full-length to paired-less protein isoforms." (PMID 18334930, 2008). "However, if canine aniridia is a dominant disease, there appears to be association of PAX6 with aniridia in that all affected dogs share at least one common haplotype ("111TG1")." (PMID 17417604, 2007). "In this study, we observed several novel PAX6 mutations in familial aniridia." (PMID 16803629, 2006).
aniridia (continued). "Whereas aniridia is generally caused by mutations or deletions that inactivate the protein product, a subset of aniridia patients was shown to have two intact copies of the PAX6 transcription unit." (PMID 17014839, 2006). "PAX6 is associated with the loss-of-function disorder aniridia." (PMID 15630479, 2005). "Studies on WAGR patients and aniridia patients with chromosomal rearrangements clearly demonstrated that aniridia could be caused by deletion of one copy of the PAX6 gene." (PMID 15918896, 2005). "Thus it was proposed that aniridia results from PAX6 haploinsufficiency and is caused by loss-of-function of one allele." (PMID 15918896, 2005). "Mutations of the PAX6 gene may result in a series of ocular abnormalities, including congenital aniridia, anterior segment dysgenesis (ASD), progressive corneal opacification, glaucoma, and hypoplasia of the fovea and optic nerve, leading to reduced visual acuity and even blindness." (PMID 36816037, 2023). "Congenital aniridia, affecting both the iris and other ocular structures such as the optic nerve, retina, cornea, and lens, is a complex disease caused by heterozygous mutations of the PAX6 gene or associated regulatory regions, resulting in insufficient functional PAX6 protein." (PMID 37542296, 2023). "Mutations of the PAX6 gene may induce various ocular abnormalities, including congenital aniridia, anterior segment dysgenesis (ASD), cataract, corneal opacification, glaucoma, hypoplasia of the fovea and optic nerve, and nystagmus, leading to reduced visual acuity and even blindness." (PMID 36816037, 2023). "The mRNA transcribed from a single functional allele will lead to a 50% reduction in the PAX6 protein level, which is insufficient to trigger the transcription of its downstream target genes, and consequently, hinder normal eye development and lead to aniridia." (PMID 36582291, 2022). "In situations when MLPA, aCGH, and the PAX6 gene sequencing do not identify any cause of the disease, a whole exome (WES) or whole genome sequencing (WGS) could be used for identification of novel (e.g., deep intronic) mutations in the PAX6 gene or novel genes involved in pathogenesis of aniridia." (PMID 29460221, 2018). "We used our custom WAGR array as a second-line diagnostic method to test 32 additional patients: 12 cases with isolated aniridia, one syndromic patient with aniridia and 19 patients with several other ocular malformations that could potentially be caused by PAX6 anomalies." (PMID 28231309, 2017). "In addition, a known variant (c.649C>T; p.Arg217*) in PAX6 segregated in a family with aniridia." (PMID 27463523, 2016). "Furthermore, the mutation of Pax6 causes aniridia and induces diabetes." (PMID 26262640, 2015). "Mutations in the PAX6 gene may cause aniridia, coloboma, hereditary keratitis (KERH, OMIM:148190), bilateral optic nerve hypoplasia (BONH), interhemispheric brain malformations, Peters syndrome (PAN, OMIM 604229), Gillespie syndrome (OMIM:206700), and probably myopia." (PMID 23799907, 2013). "Heterozygous Pax6 mutations cause the eye phenotype aniridia in humans, and is also associated with glucose intolerance, lack of pineal gland and absence of the anterior comissure, as well as various neural phenotypes associated with aniridia and references therein)." (PMID 22384097, 2012). "Also, we found four novel PAX6 mutations associated with aniridia." (PMID 22393275, 2012). "Background/Objectives: PAX6 haploinsufficiency-related congenital aniridia is a panocular disease affecting multiple ocular structures." (PMID 41827221, 2026). "Sensory: WFS1 is linked to optic atrophy and deafness; GLIS3 to congenital glaucoma; PAX6 to aniridia." (PMID 41614934, 2026). "Downregulation of fatty acid binding protein 5 (FABP5) has been reported in conjunctival cells of congenital aniridia patients and in limbal epithelial cells (LECs) of the PAX6 siRNA knockdown model." (PMID 42048350, 2026).
aniridia (continued). "Recent studies have highlighted the complexity of PAX6 gene splicing, particularly in exon 6, and its role in congenital aniridia." (PMID 40133207, 2025). "In congenital aniridia, PAX6 haploinsufficiency disrupts the physiological function of limbal epithelial cells, potentially impairing their interaction with limbal fibroblasts, which serve as their niche cells." (PMID 40622913, 2025). "This raises the question of how PAX6 haploinsufficiency in congenital aniridia affects the unique secretome of limbal fibroblasts, especially given that mesenchymal-derived cells typically express minimal to no PAX6." (PMID 40622913, 2025). "Taking aniridia as an example, whilst PAX6 mutations remain the predominant cause, variants in CYP1B1, FOXC1, PXDN and SOX11 have also been reported in patients with childhood glaucoma and aniridia." (PMID 41011222, 2025). "Also, given the lack of therapies targeting the underlying haploinsufficiency in congenital aniridia, it is of particular interest to evaluate whether compensating for the deficiency of miR-204-5p could lead to PAX6 normalization with beneficial downstream effects in the cornea." (PMID 39488562, 2024). "Congenital aniridia is a rare pan-ocular disease that is in most cases a result of haploinsufficiency of the PAX6 gene." (PMID 39488562, 2024). "From another participant’s viewpoint, genetic testing advances the knowledge about the PAX6 gene in hopes of helping future generations, preventing sporadic aniridia and discovering treatments." (PMID 37787878, 2024). "The regulatory role of these CREs was suggested by the existence of aniridia in patients with different chromosome 11p13 rearrangements affecting the downstream elements while preserving the PAX6 coding sequence." (PMID 38459225, 2024). "In this study, we identified a novel microdeletion with a length of 517 kb downstream of the PAX6 gene in a Chinese family with congenital aniridia, although two copies of PAX6 are intact." (PMID 37752489, 2023). "Herein, we aimed to functionally characterize four DIVs in PAX6 identified in patients with aniridia." (PMID 36675087, 2023). "The present study reports a novel intragenetic deletion of the PAX6 gene in a Chinese patient with congenital aniridia combined with ectopia lentis, cataracts, and retinal detachment." (PMID 37542296, 2023). "The results show that both rod- and cone-related functions are affected in PAX6-related aniridia and suggest that retinal anatomical and physiological changes extend beyond the area commonly studied in this condition: the central macula." (PMID 37067366, 2023). "Structural variants (SVs) on chromosome 11p13 play a crucial role in 25–30% of patients with congenital aniridia by affecting PAX6 expression." (PMID 37269011, 2023). "Microdeletions involving the 11p3q region are frequent in cases with congenital aniridia, and these microdeletions partly or completely encompass the PAX6 gene or remove the PAX6 gene." (PMID 37752489, 2023). "A novel variant (c.114_119delinsAATTTCC: p.Pro39llefsTer17) in the PAX6 gene was identified in subjects II-1, III-1 and III-2, who exhibited complete aniridia and cataracts." (PMID 35034608, 2022). "PAX6, a paired-box and homeobox domain gene is one of the principal regulators in eye development, first described as a candidate for human aniridia." (PMID 34345029, 2022). "The deletion of chromosome 11p13 involving the WT1 and PAX6 genes has been shown to cause WAGR syndrome (OMIM #194072), a rare genetic disorder that features Wilms’ tumor, aniridia, genitourinary anomalies, as well as mental retardation." (PMID 36011342, 2022). "For most genetic eye conditions, sequencing of either a single gene, such as PAX6 for aniridia in adults, or targeted gene panels, such as for retinal dystrophies, is usually considered as the initial route of molecular analysis." (PMID 35911417, 2022).
aniridia (continued). "It has been reported, for example, that patients with a deficiency in the PAX6 3′ region containing its enhancer confer ASD and moderate mental retardation, indicating the role of PAX6 in neural phenotypes in addition to aniridia." (PMID 35682795, 2022). "KRT3 and KRT12 markers are downregulated in ocular surface of subjects with aniridia and are described as being regulated by PAX6 in vitro as well." (PMID 34827649, 2021). "A Pax6-deficient mouse model of aniridia, with naturally occurring G194X stop mutation (TGA) in the mouse Pax6 gene, was used for in vivo studies." (PMID 34451881, 2021). "Only two patients presented the full classical description of PAX6-related aniridia: aniridia, nystagmus, and foveal hypoplasia, while the other two presented manifestations presented in the aniridia spectrum: partial aniridia or aniridia-related keratopathy." (PMID 34065151, 2021). "We detected a novel deletion in PAX6 responsible for congenital aniridia in the affected individuals of this Chinese family." (PMID 34610801, 2021). "DSG1 (Desmoglein-1) is a cellular junction protein, and it has been reported to be downregulated in Sey+/− (Pax6+/−) mice, which is an animal model for congenital aniridia." (PMID 34827649, 2021). "Aniridia is such a disorder, in which haploinsufficiency of PAX6 (a stem/progenitor cell gene) results in progression to blindness unhalted by current treatments." (PMID 33531684, 2021). "Clinicians should be aware of this mild aniridia phenotype and the PAX6-related congenital cataracts and request genetic testing when suspected." (PMID 34065151, 2021). "The missense variants reported in this manuscript suggest a role for MAB21L1 in microphthalmia, aniridia, and coloboma in humans, similar to the PAX6 spectrum." (PMID 33973683, 2021). "PAX6 has been identified in cases of congenital cataract, and a case series on cataract surgery in patients with congenital aniridia demonstrated some improvement in visual acuity following cataract surgery over a follow-up period of up to 18 months." (PMID 34101622, 2021). "The mouse mutation Small eye (Sey), which has been proposed as a model for aniridia, results from defects in PAX6, and the human aniridia and murine Small eye phenotypes arise from homologous defects in PAX6." (PMID 34065151, 2021). "Iris development is also sensitive to reductions in PAX6 activity, with phenotypes ranging from mild iris hypoplasia to complete aniridia." (PMID 34783308, 2021). "In conclusion, a novel 4.25 kb deletion in the PAX6 gene was found in this Han Chinese family with congenital aniridia combined with cataract and nystagmus." (PMID 34610801, 2021). "Ataluren eye drops aim to restore ocular surface PAX6 haploinsufficiency in congenital aniridia, and this new formulation opens to further clinical studies and innovative treatment for patients." (PMID 33375041, 2020). "The main genetic candidate for congenital aniridia is the paired box 6 (PAX6) gene (OMIM 607108) on chromosome 11p13." (PMID 32125788, 2020). "In the present study, all exons and flanking regions of PAX6 were screened in a Chinese family with aniridia, and a novel heterozygous deletion was detected." (PMID 30621664, 2019). "Mutations in the PAX6, PITX2, and FOXC1 genes have been associated with ARS and aniridia in an autosomal-dominant manner." (PMID 31341655, 2019). "Changes in 3’ regulatory PAX6 regions were also identified in patients presenting with classical aniridia." (PMID 31861090, 2019). "Only in two patients with aniridia, deletions downstream of the PAX6 gene including the ELP4 gene affecting the entire critical region were identified." (PMID 29460221, 2018). "Aniridia, characterized by the incomplete development of the iris and fovea, is the most frequent PAX6-related condition, with a worldwide incidence of 1:50,000–100,000 births." (PMID 30386378, 2018).
aniridia (continued). "The result of PAX6 haploinsufficiency, aniridia is a rare genetic disorder predominantly affecting the eyes, central nervous system, and pancreas." (PMID 30258099, 2018). "Aniridia has in some cases been shown to be due to defects in a sequence element located in an intron of the ELP4 gene that maps close to PAX6." (PMID 30542652, 2018). "Wilms tumor, aniridia, genitourinary anomalies and mental retardation (WAGR) syndrome is a rare genetic disorder caused by heterozygous deletions of WT1 and PAX6 at chromosome 11p13." (PMID 29061165, 2017). "Human PAX6 gene was originally identified as a responsible gene for aniridia in the chromosome region 11p13 that is responsible for WAGR (Wilim’s tumor, Aniridia, Genitourinary malformations and mental Retardation) syndrome." (PMID 27855195, 2016). "Mutations in the PAX6, PITX2, and FOXC1 genes have been associated with aniridia and ARS in an autosomal dominant manner." (PMID 27463523, 2016). "Expression of the transcription factor Pax6, whose deletion has been found to result in aniridia, autism, and mental retardation in humans, was localized to the sensory epithelia at W9 among the supporting cells as well in the surrounding mesenchymal tissue." (PMID 27895556, 2016). "PAX6 (OMIM 607108), a well-known aniridia disease-causing gene located in chromosome 11p13 region, contains 14 exons and encodes a protein of 422 amino acids." (PMID 25628759, 2015). "In this study, we report on a novel genomic microdeletion including PAX6 in a small Chinese family with aniridia, cataract, ptosis and mental retardation detected by SNP-array assay." (PMID 25628759, 2015). "The 518 kb heterozygous deletion in 11p13 encompassing PAX6 should be the genetic etiology for the familial aniridia." (PMID 25628759, 2015). "For example, a deletion in case 16 encompassing WT1 and PAX6 caused 46,XY DSD, Wilms tumor, aniridia, and mental retardation, which is collectively referred to as WAGR syndrome." (PMID 26542297, 2015). "Individuals with PAX6-mediated aniridia have insufficient levels of PAX6 protein, which is expressed in the eye, cerebellum, olfactory bulb and throughout the cerebral cortex in early human brain development, but is not expressed cortically in the adult." (PMID 25566032, 2014). "Previous studies have indicated that the normal development of the mammalian eye is dependent on the level of PAX6 and insufficient expression levels of PAX6 lead to pan-ocular disorders, such as aniridia." (PMID 24939714, 2014). "The PAX6 messenger ribonucleic acid level was about 50% lower in patients with aniridia than in unaffected family members in FAMILY-1." (PMID 23734086, 2013). "The PAX6 mRNA level was about 50% lower in patients with aniridia than in unaffected family members in FAMILY-1." (PMID 23734086, 2013). "The distant downstream region in particular has been shown to be essential for Pax6 expression as its heterozygous removal through deletion or translocation leads to the eye malformation aniridia in human patients." (PMID 23359656, 2013). "Defects in the PAX6 gene expression in mice have aniridia-like iris anomalies, corneal opacities and lens-corneal adhesions that resemble Peters’ anomaly." (PMID 24250932, 2013). "Real-time PCR was used to determine the PAX6 messenger ribonucleic acid(mRNA) level in patients with aniridia and in unaffected family members." (PMID 23734086, 2013). "This deletion was found to be distal to PAX6, a region where similar deletions have previously been found in patients affected by aniridia." (PMID 22912880, 2012). "In the present study, we found a novel PAX6 deletion in a Chines family affected by congenital aniridia." (PMID 22550392, 2012). "To demonstrate the program's usefulness, we used CNViewer to identify a deletion distal to PAX6 that co-segregates with individuals affected by aniridia in one family." (PMID 22912880, 2012).